MBP (myelin basic protein)
Diseases named in the same sentence as MBP in open-access papers (continued):
Sharing a sentence is not in itself a finding about the gene and the disease.
multiple sclerosis (continued). "Antibodies hydrolyzing myelin basic protein have been found and described in detail in multiple sclerosis (MS), systemic lupus erythematosus (SLE), autism, and schizophrenia." (PMID 35806400, 2022). "In the multiple sclerosis model induced in rats, the daily administration of TQ alleviated myelin basic protein-induced autoimmune encephalomyelitis by inhibiting the NF- κB activation in the brain and spinal cord." (PMID 35958317, 2022). "Immunodominant MBP epitopes are concealed within intact myelin and, when released by proteases, contribute to pathogenesis of autoimmune demyelinating conditions, multiple sclerosis, and Guillain-Barre syndrome." (PMID 35496906, 2022). "The loss of this function is related to multiple sclerosis; exaggerated AEP protease activity destroys the myelin basic protein (MBP) peptides, leading to the failure of immune tolerance in the thymus against MBP." (PMID 34068767, 2021). "Myelin basic protein (MBP) is a potential autoantigen in multiple sclerosis (MS), and a mouse model of MS showed a correlation between MBP binding to CR3 and experimental autoimmune encephalitis (EAE)." (PMID 33995387, 2021). "In 1993, Weiner and collaborators treated patients with multiple sclerosis for one year with 300 mg of bovine myelin that contains MBP and PLP similar to human myelin." (PMID 35919733, 2021). "In this study, electrophoretically homogeneous IgGs against H1, H2A, H2B, H3, and H4 histones and myelin basic protein (MBP) were isolated from the blood sera of multiple sclerosis (MS) patients by several affinity chromatographies." (PMID 34439806, 2021). "MBP is one of the major myelin sheath autoantigens in multiple sclerosis (MS) and animal models of autoimmune neurological disorders." (PMID 34827627, 2021). "In the central nervous system (CNS), myelin basic protein (MBP) or myelin oligodendrocyte glycoprotein (MOG) can be targeted in multiple sclerosis (MS)." (PMID 34552599, 2021). "In patients with multiple sclerosis (MS), some studies have shown an increase in the prevalence of antibodies to gliadin and myelin basic protein (MBP)." (PMID 35366249, 2021). "Autoantibodies-abzymes hydrolyzing DNA, myelin basic protein, and oligosaccharides have been revealed in the sera of patients with multiple sclerosis (MS)." (PMID 33802122, 2021). "HLA-DRB1*0401-restricted MBP 111–129-specific Humanized TCP transgenic mice emulating multiple sclerosis (MS) presented dysphagia induced by restriction in mandible and tongue movement." (PMID 34067192, 2021). "Removal of arginine occurs at several sites and has been increased in multiple sclerosis, and the degree of removal (or citrullination) of MBP correlates with the severity of multiple sclerosis." (PMID 34827627, 2021). "Myelin basic protein (MBP) is thought to be one of the key autoantigens in multiple sclerosis (MS) development." (PMID 32431704, 2020). "On the other hand, we found decreased phosphorylated MBP levels as others did previously in multiple sclerosis patients’ and cuprizone mice’s brains." (PMID 32272486, 2020). "Abzymes capable of hydrolyzing MBP were found and studied in detail in multiple sclerosis, systemic lupus erythematosus, and in the serum of autistic children." (PMID 32851101, 2020). "Myelin basic protein (MBP) and its interaction with lipids of the myelin sheath plays an important part in the pathology of multiple sclerosis (MS)." (PMID 33028889, 2020). "It was recently shown that IgGs from sera of multiple sclerosis (MS) patients are active in the hydrolysis of DNA and myelin basic protein (MBP)." (PMID 32325782, 2020). "Recently, we reported an ELISA study showing that titers of autoantibodies against MBP in patients with schizophrenia are ~1.8 fold higher than in healthy individuals, but 5.0-fold lower than in patients with multiple sclerosis." (PMID 32851101, 2020).
multiple sclerosis (continued). "The TCR-like mAb MK16 is specific for a myelin basic protein (MBP)-derived peptide, one of the proposed autoantigens in multiple sclerosis (MS), bound to the disease-associated HLA-DR2b molecule and was used to assess peptide-presentation in patient tissue." (PMID 31544838, 2019). "Apitopes have successfully induced self-tolerance in multiple sclerosis, and the mixture of myelin basic protein (MBP) peptides used (ATX-MS-1467) is currently in Phase IIb development." (PMID 31194638, 2019). "As an example, in multiple sclerosis, it was proposed that an antigen-specific T-cell receptor cross-react with a self-antigen, the myelin-basic-protein (MBP) and a peptide analogous to part of a viral antigen, the polymerase of the Epstein-Barr virus." (PMID 31850365, 2019). "MMP-9 has been shown to cleave organ-specific aAg, such as myelin basic protein in multiple sclerosis, collagen in arthritis, insulin in diabetes, and ubiquitous aAg in systemic autoimmune diseases." (PMID 30967870, 2019). "In case of multiple sclerosis (MS), the autoreactive responses are though to be in part directed against myelin basic protein (MBP)." (PMID 29367624, 2018). "Multiple sclerosis (MS) is a chronic neurodegenerative disease that affects protein constituents within the myelin sheath, such as myelin basic protein (MBP), myelin oligodendrocyte glycoprotein, and proteolipid protein." (PMID 30518150, 2018). "In this report, amide-linked cyclic peptide analogues of the 87–99 myelin basic protein (MBP) epitope, a candidate autoantigen in multiple sclerosis (MS), are tested for therapeutic efficacy in experimental autoimmune encephalomyelitis (EAE)." (PMID 29385090, 2018). "In patients presenting with a first demyelinating event (FDE), the presence of serum antibodies against MBP significantly predicted conversion to multiple sclerosis (MS) in some but not all studies." (PMID 28413712, 2017). "Schmierer et al27, in a study of PM tissues from patients with multiple sclerosis using 9.4T MRI, showed an inverse correlation between MBP and T2 in the cortex and an inverse correlation between MBP and T1 in the white matter." (PMID 26268959, 2016). "This encompassed a search for naturally occurring, cross-reactive, environmental ligands for a prototypic, multiple sclerosis patient-derived T cell receptor specific for myelin basic protein epitope." (PMID 25962509, 2015). "Myelin basic protein (MBP) is one of the major autoantigens in the pathogenesis of multiple sclerosis (MS) and experimental autoimmune encephalomyelitis —animal model of MS." (PMID 25276831, 2014). "It was found that antibodies (Abs) against myelin basic protein (MBP) are the major components of the antibody response in multiple sclerosis (MS) patients." (PMID 25265393, 2014). "Phosphorylation of MBP is altered during development and ageing, and the overall level is decreased in multiple sclerosis." (PMID 23861868, 2013). "Elevated serum levels of MBP have been observed in ischemic stroke and autoimmune diseases such as multiple sclerosis, reflecting BBB disruption and demyelination process." (PMID 23874584, 2013). "In this model, T cells express a transgenic T cell receptor (TCR) specific for the Myelin Basic Protein (MBP) peptide Ac1-9, making the animals susceptible to experimental autoimmune encephalomyelitis (EAE), a disease akin to multiple sclerosis in humans." (PMID 23593464, 2013). "The predominant 18.5-kDa isoform of MBP is an intrinsically-disordered protein that is a candidate auto-antigen in the human demyelinating disease multiple sclerosis." (PMID 23861868, 2013). "The patients' families were subsequently examined for the myelin basic protein (MBP) gene on chromosome 18, which is a candidate gene involved in multiple sclerosis." (PMID 24324888, 2013). "For example, in a mouse model of multiple sclerosis, ectopic expression of neuronal autoantigen myelin basic protein (MBP) in the liver prevented the development of the disease." (PMID 24069022, 2013).
multiple sclerosis (continued). "In the brain, PAD2 citrullinates myelin basic protein (MBP), a major component of the myelin sheath and this activity has been found to be elevated in multiple sclerosis." (PMID 22911765, 2012). "CBLB plays a critical role in antigen-induced immune tolerance and Cblb-deficient mice immunized with myelin basic protein are more susceptible to experimental autoimmune encephalomyelitis (EAE), a model for multiple sclerosis." (PMID 23036268, 2012). "MBP gene and protein expression have been found altered consistently in schizophrenia and multiple sclerosis." (PMID 22350622, 2012). "We recently demonstrated a close association between active cerebral lesions in multiple sclerosis (MS) and CD4+ T cell proliferation and mononuclear cell (MNC) production of IL-17 and IL-5 induced by myelin basic protein (MBP) ex vivo." (PMID 21625457, 2011). "MBP is a well-known target autoantigen in multiple sclerosis (MS), a human neurodegenerative disease with an active destruction of myelin sheath." (PMID 21673997, 2011). "Interest in MBP has centered on its role in demyelinating diseases, particularly multiple sclerosis (MS)." (PMID 21696608, 2011). "Antibodies to MBP are the major component of autoantibodies in multiple sclerosis, a human autoimmunity with a neurodegenerative phenotype." (PMID 21673997, 2011). "For example the acetylated N-terminal peptide of myelin basic protein is found to be required for development of experimental autoimmune encephalomyelitis (EAE) - a murine model of human multiple sclerosis." (PMID 20485683, 2010). "The limitations outweigh the usefulness of evaluating MBP levels in the CSF due to which measurement of CSF MBP levels is not the standard of care in routine analysis of CSF of patients with multiple sclerosis." (PMID 20182572, 2009). "Measurement of CSF MBP levels in multiple sclerosis is sometimes used to confirm a clinical exacerbation as elevated levels are generally not seen in patients during periods of remission." (PMID 20182572, 2009). "A calcium-dependent interaction between human MBP and CaM has previously been reported for two MBP charge isoforms isolated from a patient suffering from multiple sclerosis, as have calcium-dependent interactions between bovine and murine MBP and CaM." (PMID 18284662, 2008). "In trials of APL in multiple sclerosis, increased reactivity to APLs and the native myelin basic protein were noted." (PMID 17645792, 2007). "There are examples of people who produce abzymes with potentially clinically significant effects, for example, DNA, immunoglobulin, vasoactive intestinal peptide (VIP), myelin basic protein (MBP) in persons with multiple sclerosis, and factors in the coagulation cascade (39, –, 41)." (PMID 40693778, 2025). "Also, the loss of BIN1 parallels myelin loss in multiple sclerosis brain lesions neurodegeneration, and DDX5 is involved in MBP regulation." (PMID 40943121, 2025). "Also, proteins encoded by human orthologs of PLP1, MBP, and MOBP are known to be antigens recognized by CD4+ T cells in multiple sclerosis patients." (PMID 36817487, 2023). "It has been suggested that MBP may play a role in the progression and potential treatment of multiple sclerosis; however, it is unclear what role it has in gcGBM biology." (PMID 37377888, 2023). "In the blood serum of patients with multiple sclerosis, immunoglobulins (Ig) hydrolyzing myelin basic protein (MBP) (IgG, IgA and IgM), as well as IgGs with catalytic activity to histones and to oligodendrocyte progenitor cell surface proteins of oligodendrocyte precursors have been reported." (PMID 37431466, 2023). "Similarly, Tregs expressing a myelin basic protein-specific (MBP) TCR ameliorated the severity of disease in mouse models of multiple sclerosis." (PMID 38136421, 2023).
multiple sclerosis (continued). "It should be noted that the relative activity of antibodies from the cerebrospinal fluid of multiple sclerosis patients in the hydrolysis of DNA, MBP, and polysaccharides, depending on the substrate, is 30–60 times higher than that from the blood of the same patients." (PMID 36901861, 2023). "It was interesting whether the IgGs of multiple sclerosis patients against histones are also capable of splitting the five histones and MBP and vice versa." (PMID 36289924, 2022). "In this context, it is notable that multiple sclerosis patients’ T cells appear to preferentially respond to citrullinated MBP, which suggests that citrullination of MBP may be involved in the induction or perpetuation of multiple sclerosis." (PMID 36896314, 2022). "Furthermore, propranolol improved functional disability, tremors, and ataxia in multiple sclerosis, restoring MBP." (PMID 35893792, 2022). "Further studies based on a larger cohort of recently diagnosed and untreated MS patients could contribute to clarify the role of MBP in Multiple Sclerosis." (PMID 35795217, 2022). "Similarly, patients with multiple sclerosis (MS), have increased levels of citrullinated myelin basic protein, which leads to demyelination of the myelin sheath reducing nerve signal transduction." (PMID 36077232, 2022). "Anti-MBP antibodies are typically present in approximately 50% of multiple sclerosis (MS) patients." (PMID 35073943, 2022). "Here, we have shown for the first time, using IgG–abzymes from patients with multiple sclerosis, that IgGs against H3, H1, H2A, H2B, H4, human MBP, and DNA possess an ability similar to anti-H3 IgGs to form complexes with the H3 histone, demonstrating polyreactivity in complexation." (PMID 36289924, 2022). "AZE can misincorporate in place of proline in myelin basic protein (MBP) and this has been hypothesised to be implicated in the pathogenesis of multiple sclerosis (MS)." (PMID 33547590, 2021). "In this article, we have first shown, on the example of IgGs from patients with multiple sclerosis, that IgGs against H2A, H2B, H3, H4, and myelin basic protein possess an ability similar to anti-H1 IgGs to form complexes with H1 histone, demonstrating polyreactivity in complexation." (PMID 34439806, 2021). "High levels of KLK6 may favor the progression of multiple sclerosis through an excessive cleavage of myelin basic protein, the most widely studied myelin protein in this disease." (PMID 32655372, 2020). "Myelin basic protein (MBP) may play a decisive role in the elucidation of multiple sclerosis, particularly for the early stages in progression of this highly debilitating, demyelinating autoimmune disease." (PMID 32106542, 2020). "Tg4 mouse T cells recognize the Ac1-9 N-terminal peptide AcASQKRPSQR from myelin basic protein (MBP), an encephalitogenic auto-Ag associated with multiple sclerosis, and can be rendered tolerant by repeated exposure to the higher affinity, MHC-binding MBP Ac1-9[4Y] analog AcASQYRPSQR (4Y)." (PMID 32521273, 2020). "MBP autoantibodies had already been described in the CSF of patients with multiple sclerosis (MS)." (PMID 31379804, 2019). "More specifically, cross-reactivity between BSA and human autoantigens, e.g., collagen type I, vitamin D binding protein, myelin basic protein and islet beta cells, has been reported in patients with rheumatoid arthritis, multiple sclerosis, and diabetes mellitus." (PMID 30333817, 2018). "MBP is a target in multiple sclerosis and differences in its content may influence the fate of axons in brain pathologies." (PMID 30406183, 2018). "Further, T cells reacting with immunodominant epitopes of myelin basic protein (MBP) cross-react with certain viral antigens and therefore may have a likelihood to induce multiple sclerosis." (PMID 29062305, 2017).
multiple sclerosis (continued). "Notably, citrullinated MBP accounts for 45% of the total MBP in multiple sclerosis (MS) patients and for more than 80% in fulminant MS patients, whereas 20% of MBP is citrullinated in healthy brain and other neurological disorders." (PMID 29077055, 2017). "MBP is an abundant myelin protein involved in demyelinating diseases, such as multiple sclerosis." (PMID 28694532, 2017). "Expanded disability status scale (EDSS) as well as multiple sclerosis severity score (MSSS) correlated with reduced ability of B cells to produce IL-10 after stimulation with MBP, indicative of diminished B-cell immune regulatory function in patients with the most severe disease." (PMID 26756931, 2016). "Reduced myelin basic protein-induced CD4+ T-cell autoreactivity in interferon-β-treated multiple sclerosis patients may be mediated by monocyte-derived interleukin-10." (PMID 25738751, 2015). "Multiple sclerosis may originate in some cases by cross-recognition of EBV-specific T cells with an epitope in myelin basic protein (MBP) restricted by HLA-DRB1*1501." (PMID 26270649, 2015). "Interestingly, glatiramer acetate (GA), which is used to treat multiple sclerosis (MS) and is structurally similar to MBP, inhibits intracellular and in vitro proteasome-mediated MBP degradation." (PMID 25276831, 2014). "In contrast, the multiple sclerosis protective allele DRB1*16:01 formed this stable complex only with the MBP peptide but not with the viral peptide." (PMID 25101830, 2014). "Interestingly, MBP, in addition to the myelin oligodendrocyte glycoprotein, is also one of the major autoantigens identified in multiple sclerosis (MS)." (PMID 24739384, 2014). "Additionally, Matrix metalloproteinases (MMPs) are reported to play a significant role in the fragmentation of MBP and demyelination leading to multiple sclerosis and EAE." (PMID 23635033, 2013). "In later reports, peptides from myelin basic protein (MBP) and other autoantigens were identified in central nervous system (CNS) samples from multiple sclerosis (MS) patients, and peptides from collagen, vimentin, and others were detected in synovial samples from rheumatoid arthritis (RA) patients." (PMID 24381570, 2013). "We have previously demonstrated that high frequencies of T cells directed against the self-antigen MBP peptide 85–99 in the peripheral blood of patients with multiple sclerosis (MS) fail to proliferate when stimulated with antigen but readily secrete high levels of cytokine." (PMID 23186108, 2012). "Furthermore, in the experimental autoimmune encephalomyelitis (EAE) mouse model for multiple sclerosis, myelin basic protein (MBP)-specific Treg cells were detected and protection was associated with specificity for MBP." (PMID 19751267, 2009). "Several segments of MBP are target autoantigens that have been characterised in multiple sclerosis." (PMID 18284662, 2008). "Hydrolysis of a multiple sclerosis (MS) autoantigen, myelin basic protein (MBP), by engineered human proteasomes with different catalytic phenotypes, revealed that peptides which may be directly loaded on the HLA class I molecules are produced mainly by immunoproteasomes." (PMID 36768413, 2023). "However, antibodies against MBP are also prevalent in patients with Multiple Sclerosis." (PMID 35073943, 2022). "In the particular case of multiple sclerosis (MS), there are strong indications that the loss of tolerance is directed toward various myelin proteins, including myelin oligodendrocyte glycoprotein (MOG), myelin basic protein (MBP), and proteolipid protein (PLP)." (PMID 33679769, 2021). "Indeed, it has been reported that UA increased the myelinated area, oligodendrocyte count and myelin basic protein (MBP) content in a multiple sclerosis mouse model after administration for six weeks, as UA acted as an agonist of peroxisome proliferator activated receptor γ (PPARγ)." (PMID 33925641, 2021). "MBP may aid in the clinical evaluation of multiple sclerosis and stroke." (PMID 31035713, 2019).